MIR4672 (microRNA 4672)
Synonyms: hsa-mir-4672
Gene: MicroRNA gene on chromosome 9 (127,869,415 to 127,869,495, reverse strand). Ensembl gene ENSG00000263979.
Homologues: Orthologues: chimpanzee MIR4672 (100% identical).